CGAS (cyclic GMP-AMP synthase)
Diseases named in the same sentence as CGAS in open-access papers (continued):
Sharing a sentence is not in itself a finding about the gene and the disease.
Lewis lung carcinoma (3 papers, 2020 to 2024). "Knockdown of cGAS suppresses DNA damage and inhibits the growth of Lewis lung carcinoma (LLC) cells both in vitro and in vivo, uncovering a tumor-promoting role of nuclear cGAS." (PMID 34374004, 2022). "STING agonists also induced tolerogenic responses that promoted Lewis Lung Carcinoma (LLC) growth in mice by stimulating IDO activity in inflamed lymph nodes draining sites of tumor growth, though cGAS was not essential to induce IDO1 in the LLC model." (PMID 32625215, 2020).
lysosomal storage disease (3 papers, 2024 to 2025). A metabolic disorder caused by mutations in proteins critical for lysosomal function, including lysosomal enzymes, lysosomal integral membrane proteins, and proteins involved in the post-translational modification and trafficking of lysosomal proteins. "In lysosomal storage diseases, impaired mitophagy results in the accumulation of dysfunctional mitochondria; these release mtDNA into the cytosol and activate innate immune signaling through the cGAS–STING pathway." (PMID 41573578, 2025).
osteoporosis (3 papers, 2021 to 2025). A condition of reduced bone mass, with decreased cortical thickness and a decrease in the number and size of the trabeculae of cancellous bone (but normal chemical composition), resulting in increased fracture incidence. "In summary, this study reveals that WSTLZTD ameliorates osteoporosis by regulating macrophage senescence via LONP1, thereby suppressing cGAS/STING pathway activation in BMSCs to enhance osteogenic differentiation (Created in BioRender)." (PMID 40719285, 2025). "WSTLZTD potentially modulate macrophage senescence via LONP1, which subsequently suppresses the activation of the cGAS/STING pathway in BMSCs, ultimately promoting their osteogenic differentiation and ameliorating osteoporosis." (PMID 40719285, 2025). "Data above all showed that the cGAS-STING signal pathway had a certain regulatory effect on macrophages polarization and T lymphocytes differentiation in osteoporosis, TBI, IS, and MI." (PMID 34956229, 2021).
ovarian tumor (3 papers, 2021 to 2024). "Previous studies using ovarian tumor–bearing mice show cisplatin can activate the cGAS/STING pathway and T cell recruitment, indicative of innate priming and an adaptive immune response to this treatment." (PMID 34549724, 2021). "This hypothesis is supported by findings indicating that the cGAS-STING signaling is typically inhibited in ovarian tumor cells, suggesting a mechanism to clear collapsing micronuclei and prevent DNA released into the cytoplasm." (PMID 38867360, 2024).
overnutrition (3 papers, 2020 to 2024). An imbalanced nutritional status resulting from excessive intake of nutrients. "For example, mitochondrial stress in adipocytes caused by overnutrition or fatty acid accumulation can lead to the release of mtDNA, which activates the cGAS-STING pathway." (PMID 39669992, 2024). "Collectively, overnutrition, cytokines, and cytosolic DNA serve as activators of cGAS-STING signaling in various adipose cell types, contributing to widespread inflammation and metabolic dysfunction." (PMID 39669992, 2024). "Overnutrition, mtDNA, cGAMP or LPS can stimulate cGAS-STING and activate downstream effectors, such as proinflammatory cytokines, monocyte infiltration regulators and metabolism-related proteins." (PMID 38164186, 2024).
STING-associated vasculopathy with onset in infancy (3 papers, 2018 to 2022). "STING-associated vasculopathy with onset in infancy (SAVI) is another lupus-like disease with a link to the cGAS/STING pathway that is the consequence of the uncontrolled activation of the pathway." (PMID 35406723, 2022).
varicella (3 papers, 2023 to 2025). "In a more recent publication, the same group identified a boy with complicated varicella who had a polymorphism in the cyclic GMP-AMP synthase-stimulator of interferon genes (cGAS-STING) pathway." (PMID 39818965, 2025). "Varicella‐Zoster virus tegument protein ORF9 can bind to cGAS and form condensates with DNA, which inhibiting cGAS to produce cGAMP, and eventually causing chickenpox and shingles." (PMID 36875159, 2023). "On the other hand, one study identified an important role of STING in mounting type I and type III IFN responses to VZV in human dermal fibroblasts and HaCaT keratinocytes with potential implications for varicella pathogenesis and suggesting an important role of cGAS-STING in the skin." (PMID 38277122, 2024).
acute lung injury (2 papers, 2023 to 2024). A condition of lung damage that is characterized by bilateral pulmonary infiltrates (pulmonary edema) rich in neutrophils, and in the absence of clinical heart failure. "Acute lung injury (ALI) is a severe condition characterized by inflammation, tissue damage, and persistent activation of the cyclic GMP-AMP (cGAS)-stimulator of interferon genes (STING) pathway, which exacerbates the production of pro-inflammatory mediators and promotes the progression of ALI." (PMID 39840115, 2024).
allergic asthma (2 papers, 2023 to 2025). A asthma with a basis in a pathological type I hypersensitivity reaction. "The implication of epithelial cGAS in murine models of allergic asthma was reported, as cytosolic dsDNA accumulated in the airway epithelium of ovalbumin- or house dust mite-challenged mice, and deletion of cGAS in airway epithelial cells attenuated allergic airway inflammation." (PMID 40276777, 2025). "Further, pharmacological blocking of cGAS protected from birch pollen-induced type 2 immune responses, validating the contribution of cGAS to allergen-induced type 2 immune responses that may represent a potential therapeutic target for allergic asthma." (PMID 40276777, 2025). "Furthermore, the relative contributions of cGAS and STING pathways warrants further investigation in future studies, especially in the clinical context of human allergic asthma." (PMID 40276777, 2025). "However, the role of the DNA sensor cGAS/STING per se in allergic asthma is not fully characterized, as well as the relative role of self-dsDNA-induced type I IFNs on the Th2 responses." (PMID 40276777, 2025).
aneuploidy (2 papers, 2022 to 2024). Chromosomal disorder consisting of the presence a chromosomal abnormality in which there is an addition or loss of chromosomes within a set. "This may also explain the discrepancy between the expected cGAS expression and aneuploidy trends as there may be a more nuanced relationship between the specific type of aneuploidy and cGAS expression trends." (PMID 38473384, 2024). "As the cGAS-STING pathway is intimately associated with the immune response, the activation of the immune system in cells with CIN/aneuploidy may partly result from the activation of the cGAS-STING pathway." (PMID 36003402, 2022).
bacteremia (2 papers, 2023 to 2025). "BNx also induced gut leakage, as evident by elevated levels of blood FITC-dextran, endotoxin, bacteremia, and bacterial cell-free DNA in both WT and cGAS−/− mice." (PMID 37189826, 2023). "While our data do not directly interrogate PPP involvement in bacterial sepsis, this finding aligns with our observation of increased OXPHOS activity and suggests that similar metabolic shifts may shape inflammatory polarization in macrophages through the cGAS-STING axis." (PMID 40507879, 2025).
bladder tumors (2 papers, 2021 to 2022). "We investigated the involvement of cGAS-STING axis in a spontaneous model of persistent BPV infection of urothelial cells resulting in bladder tumors in cattle." (PMID 36311756, 2022). "Therefore, the effect of BCG treatment on bladder tumors is independent of TLR3 and the cGAS-STING pathway." (PMID 34341449, 2021).
brain hemorrhage (2 papers, 2023). "Genetic deletion of cGAS in mice also significantly reduces brain hemorrhage while on the contrary, cGAMP injection counteracts the effect of DNase-I treatment suggesting a critical role for the DNA sensor cGAS." (PMID 37187738, 2023).
brain tumor (2 papers, 2022 to 2023). "Correlation between the levels of DNA‐PKcs or cGAS and tumor grades in surgical specimens of human brain tumors." (PMID 36574362, 2023).
cerebral infarct (2 papers, 2020 to 2022). "In addition, therapeutically inhibiting cGAS via A151 or cGAS inactivation by genetically deleting also exhibited significantly reduced infarcts at day 1 after MCAO, suggesting cGAS inactivation may reduce volumes of cerebral infarct in early stages of ischemic injury development." (PMID 32239625, 2020).
cervical tumor (2 papers, 2019 to 2026). "We confirmed the expression of cGAS and STING proteins in clinical cervical tumor samples using IHC." (PMID 41624260, 2026).
Chagas disease (2 papers, 2020 to 2023). A parasitic infection caused by Trypanosoma cruzi. "We propose that small molecule PARP1 inhibitors offer a potential therapy for controlling the pathologic chronic inflammation in Chagas disease through modulation of the Mφ signaling of cGAS- NF-κB pathway." (PMID 32315358, 2020). "Overall, these studied profoundly demonstrate that cGAS-STING acts as a protagonist of innate immunity against T. cruzi infection, and the vaccines formulated based on this signaling may be effective in the Chagas disease treatment." (PMID 36825026, 2023). "Furthermore, these researches showed short-term treatment with cGAS antagonists or PARP1 inhibitors was sufficient to potently suppress TEv-induced cytokines’ expression in macrophages, which offered a potential therapy for controlling Chagas disease." (PMID 36825026, 2023).
clear cell renal cell carcinoma (2 papers, 2023 to 2024). "Cuproptosis has been shown to enhance cancer immunity by activating the cGAS-STING signaling pathway in clear cell renal cell carcinoma cells." (PMID 38778403, 2024).
COPA syndrome (2 papers, 2022). "Overall, this study shows that the type I IFN signature described in COPA syndrome patients is caused by a spontaneous activation of the cGAS/STING pathway." (PMID 35484149, 2022). "A role for cGAS in STING-mediated COPA syndrome is still controversial, as some studies have shown cGAS dependency not all of them." (PMID 36359882, 2022). "However, the mechanism of cGAS activation in COPA syndrome remains speculative and requires further investigation." (PMID 35484149, 2022). "Finally, we demonstrate that inflammation in COPA syndrome patient peripheral blood mononuclear cells and COPI-deficient cell lines is ameliorated by treatment with the small molecule STING inhibitor H-151, suggesting targeted inhibition of the cGAS/STING pathway as a promising therapeutic approach." (PMID 35484149, 2022). "This phenotype was ablated in cGAS−/−/SURF4−/− THP-1 cells (preliminary data) further supporting the requirement of cGAS as the initial driver for STING accumulation at the Golgi and subsequent inflammatory signalling in COPA syndrome." (PMID 35484149, 2022). "However, despite this increased activation, it is no longer possible to activate cGAS with transfected cytoplasmic DNA, indicating that this is a breakpoint in the pathway that is impacted in COPA syndrome." (PMID 35484149, 2022). "Therefore, our study provides hope that targeting the cGAS/STING pathway directly, for example with a STING inhibitor such as H-151, may be more specific and thus proves a greater beneficial approach to control type I IFN-mediated symptoms in COPA syndrome." (PMID 35484149, 2022).
diffuse large B-cell lymphoma (2 papers, 2023 to 2025). "Furthermore, genomic instability induced cGAS–STING-mediated PANoptosis in diffuse large B-cell lymphoma cell lines expressing STING, highlighting the therapeutic potential of STING agonists in STING-expressing cancer cells." (PMID 41173854, 2025).
dry eye (2 papers, 2022 to 2023). "Therefore, we propose that various pathogenic factors of dry eye may activate the cGAS-STING pathway through cytoplasmic dsDNA, which further upregulates NF-κB and IFN-α/β to mediate inflammation in dry eye." (PMID 35812407, 2022). "Immune-inflammatory responses are the core pathologies of dry eye, and increasing evidence supports a central role for the cGAS-STING pathway in autoimmune and inflammatory diseases." (PMID 35812407, 2022). "eDNA and NETs contain dsDNA, thus indicating the possibility of involvement of the cGAS-STING pathway in dry eye." (PMID 35812407, 2022). "We further proposed that the cGAS-STING pathway may participate in dry eye as a new mechanism linking dry eye and the immune-inflammatory response, thus providing a new direction for the mechanistic exploration of dry eye." (PMID 35812407, 2022). "Herein, we focused on the pathophysiology of the immune-inflammatory response in the pathogenesis of dry eye, attempted to gain insight into the involvement of dsDNA in the dry eye immune response, and investigated the mechanism of the cGAS-STING pathway involved in the immune-inflammatory response." (PMID 35812407, 2022). "To verify our hypothesis, we will first detect the association between the cGAS-STING pathway and dry eye in mice." (PMID 35812407, 2022). "Notably, the activation of the cGAS-STING pathway was activated in dry eye patients." (PMID 37735446, 2023). "Finally, we discussed the possibility of the cGAS-STING pathway as a new mechanism in dry eye." (PMID 35812407, 2022). "In our study, we found that the cGAS-STING pathway was elevated in in vivo mouse model, dry eye patients, and an in vitro cell culture model." (PMID 37735446, 2023). "Overall, these results provide evidence of the activation of the cGAS-STING pathway in both mouse models of ocular surface disease and dry eye patients." (PMID 37735446, 2023). "The mRNA and protein levels of cGAS, STING, TBK1, IRF3, NF-κB and inflammatory cytokines (INF-α/β, IL-6 and CXCL10) in the cornea of normal and dry eye mouse models will be detected by PCR and Western blot." (PMID 35812407, 2022). "Hence, the cGAS-STING pathway may also be involved in dry eye." (PMID 35812407, 2022). "The protein levels of cGAS and STING were increased in dry eye patients." (PMID 37735446, 2023). "Activation of the cGAS-STING pathway induced the expression of CXCL10, IL-6 and IFN-β, which were reported to be increased in dry eye patients and dry eye mice, and CXCL10 could potentially serve as a biomarker of dry eye." (PMID 37735446, 2023). "In summary, although there is no direct evidence that the pathogenesis of dry eye is related to the cGAS-STING pathway, when combined with the current research evidence, we propose that the cGAS-STING pathway may be a new mechanism involved in dry eye." (PMID 35812407, 2022).
encephalitis (2 papers, 2020 to 2024). An acute inflammatory process affecting the brain parenchyma. "For example, herpes simplex virus 1 (HSV-1), the dsDNA virus that is the most common cause of fatal sporadic encephalitis, has multiple gene products that can interfere with the cGAS-STING signaling pathway." (PMID 33042875, 2020). "For instance, Dengue virus (DENV) that can cause encephalitis has been shown to target cGAS for degradation and prevent it from detecting released mitochondrial DNA in human monocyte-derived dendritic cells and monocytic and fibroblastic cell lines." (PMID 33042875, 2020).
epilepsy (2 papers, 2025 to 2026). A brain disorder characterized by episodes of abnormally increased neuronal discharge resulting in transient episodes of sensory or motor neurological dysfunction, or psychic dysfunction. "Recently, in a deeper intestinal microscopic mechanism, it was found that gut microbiota metabolites mediate the Bax gene to reduce neuronal apoptosis through the cGAS/STING axis in epilepsy." (PMID 39915895, 2025).
fungal infections (2 papers, 2023 to 2025). "A mounting body of evidence points to a close association between cGAS-STING signaling and fungal infections, with Candida albicans and Aspergillus fumigatus-induced fungal infections being the most extensively studied." (PMID 41459537, 2025).
glaucoma (2 papers, 2023 to 2024). Increased pressure in the eyeball due to obstruction of the outflow of aqueous humor. "In the present study, we aimed to explore the potential mechanism underlying RGCs loss in glaucoma and the contribution of cGAS/STING signaling to the loss of RGCs in response to DNA stress." (PMID 38848144, 2024). "In the present study, we found that cGAS-STING is activated in the glaucoma retina of the hypertonic saline-induced mouse model." (PMID 38848144, 2024). "Targeting the cGAS-STING signaling pathway represents a potential way to alleviate glaucoma-related visual function." (PMID 38848144, 2024). "Taken together, this study presented that the glaucoma retina showed significant DNA damage along with the activation of cGAS-STING, which is followed by cell death, inflammation, as well as mitochondria dysfunction-related lipid oxidation." (PMID 38848144, 2024). "The cGAS-STING signaling represents a potential therapeutic strategy for glaucoma." (PMID 38848144, 2024). "We found the mRNA expression of cGAS-STING signaling downstream genes Il6, Ifnb, and Cxcl10 were increased in glaucoma as compared to the sham group." (PMID 38848144, 2024). "Our data demonstrate that suppression of cGAS-STING represents a promising way to ameliorate retinal inflammation and protect visual function in glaucoma." (PMID 38848144, 2024). "To confirm the effect of the cGAS-STING pathway on the progression of glaucoma, we utilized STING inhibitor C176 to treat HS-induced glaucoma." (PMID 38848144, 2024). "Correspondingly, elevated expressions of cGAS and STING were found in retinal samples from human glaucoma donors." (PMID 37726272, 2023). "To explore whether cGAS-STING signaling is involved in the pathology of glaucoma, we investigated the mRNA expression of cGAS and STING and found that cGAS and STING were significantly upregulated in the glaucoma retina." (PMID 38848144, 2024). "Suppression of cGAS-STING ameliorated inflammation and protected visual function in glaucoma mice." (PMID 38848144, 2024). "Notably, IHC showed that cGAS, STING, GSDMD, and Caspase-1 were significantly upregulated in the retinas of glaucoma patients." (PMID 37726272, 2023).
glomerular disease (2 papers, 2023 to 2025). "Targeting this pathway (cGAS/STING) may represent another therapeutic option to treat or even prevent glomerular disease development and/or progression." (PMID 37564655, 2023). "While we observed a significant impact of the cGAS-STING pathway on podocyte damage in glomerular diseases of both metabolic (DKD) and non-metabolic (AS and FSGS) origin, the mechanism behind it remains unclear." (PMID 37564655, 2023). "Our current findings demonstrate an important role of the cGAS-STING signaling pathway in mediating the detrimental consequences including proteinuria and glomerular dysfunction and point to STING as a potential therapeutic target in glomerular diseases of metabolic and non-metabolic origin." (PMID 37564655, 2023).
Hepatitis (2 papers, 2022 to 2025). Inflammation of the liver. "During hepatitis B virus (HBV) infection, the cGAS signaling pathway can suppress HBV replication." (PMID 35346247, 2022).
hypoxia (2 papers, 2024 to 2025). A decrease in the amount of oxygen in the body. "Future research should focus on the mechanisms and applications of cGAS/STING modulation to regulate stem cell differentiation and enhance its therapeutic effects on hypoxia‐related diseases." (PMID 39985222, 2025).
hypoxic ischemic encephalopathy (2 papers, 2024 to 2025). "For instance, Gamdzyk and his colleagues demonstrated that activation of STING through exogenous 2’3’-cGAMP could promote neuronal death and reverse the therapeutic effect of cGAS inhibitor after hypoxic ischemic encephalopathy." (PMID 39537618, 2024).